MIR103B2 (microRNA 103b-2)
Synonyms: hsa-mir-103-2-as; hsa-mir-103b-2; MIR103-2-AS; MIR103-2AS; MIRN103-2AS
Gene: MicroRNA gene on chromosome 20 (3,917,502 to 3,917,563, reverse strand). Ensembl gene ENSG00000283320.
Gene Ontology:
Biological process: miRNA-mediated post-transcriptional gene silencing
Cellular component: RISC complex